DNAL1 (dynein axonemal light chain 1)
Description:
Part of the multisubunit axonemal ATPase complexes that generate the force for cilia motility and govern beat frequency (By similarity). Component of the outer arm dynein (ODA). May be involved in a mechanosensory feedback mechanism controlling ODA activity based on external conformational cues by tethering the outer arm dynein heavy chain (DNAH5) to the microtubule within the axoneme (By similarity). Important for ciliary function in the airways and for the function of the cilia that produce the nodal flow essential for the determination of the left-right asymmetry.
Synonyms: LC1; C14orf168; MGC12435; 1700010H15RiK; CILD16
Tractability: Small molecule: a structure with a bound ligand is known. PROTAC: ubiquitination databases record sites on it; its protein half-life has been measured.
Gene: Protein-coding gene on chromosome 14 (73,644,875 to 73,703,732, forward strand). Ensembl gene ENSG00000119661.
Subcellular location: Cytoplasm, cytoskeleton, cilium axoneme
Subcellular location (Human Protein Atlas): Basal body; Cytosol; Nucleoplasm; Principal piece; Acrosome; Centriolar satellite; Centrosome; End piece; Mid piece
Gene Ontology:
Molecular function: alpha-tubulin binding; dynein heavy chain binding; protein binding
Biological process: outer dynein arm assembly
Cellular component: outer dynein arm; axoneme
Genetic constraint (gnomAD): Loss-of-function variants: 14 observed, 14.86 expected, observed/expected ratio (o/e) 0.94, 90% interval 0.62 to 1.47. The upper end of that interval is the gene's LOEUF score, 1.47, which puts it in group 6 of 6, group 1 being the genes least tolerant of losing a copy. Missense variants: 125 observed, 143.02 expected, observed/expected ratio (o/e) 0.87, 90% interval 0.75 to 1.01. Synonymous variants: 56 observed, 53.06 expected, observed/expected ratio (o/e) 1.06, 90% interval 0.85 to 1.32.
Gene-disease validity (ClinGen):
ClinGen rates the evidence that DNAL1 causes each of these diseases.
primary ciliary dyskinesia 16 (autosomal recessive): Definitive.
Homologues: Orthologues: macaque DNAL1 (99% identical), dog DNAL1 (96% identical), pig DNAL1 (95% identical), rabbit DNAL1 (95% identical), mouse Dnal1 (93% identical), rat Dnal1 (93% identical), guinea pig DNAL1 (93% identical), tropical clawed frog dnal1 (85% identical), zebrafish DNAL1 (82% identical), chimpanzee DNAL1 (81% identical), Drosophila melanogaster ODA-Dnal1 (58% identical), Drosophila melanogaster CG10839 (51% identical).
Diseases named in the same sentence as DNAL1 in open-access papers:
DNAL1 is named in the same sentence as 44 diseases in open-access papers, as found by Europe PMC text mining. Sharing a sentence is not in itself a finding about the gene and the disease. The quoted sentences say what the papers report.
primary ciliary dyskinesia (2 papers, 2021 to 2024). A rare, genetically heterogeneous, primarily respiratory disorder characterized by chronic upper and lower respiratory tract disease. "Other genomic diagnoses not included in the clinical outcome audit, include DNAL1 (Primary ciliary dyskinesia 16, MIM: 614017), SPAST (Spastic paraplegia 4, MIM:182601) and FGFR3 (Thanatophoric dysplasia, MIM:187600)." (PMID 38577897, 2024).
Huntington disease (1 paper, 2018). Huntington disease (HD) is a rare neurodegenerative disorder of the central nervous system characterized by unwanted choreatic movements, behavioral and psychiatric disturbances and dementia. "The effect of this SNP on DNAL1 is particularly interesting, as this gene is not only part of the Kyoto Encyclopedia of Genes and Genomes (KEGG) Huntington’s disease gene pathway but is also directly involved in aberrant BDNF transport." (PMID 29932126, 2018).
situs inversus (1 paper, 2019). A congenital condition in which there is complete right-to-left reversal of the position of the major thoracic and abdominal organs (that is, they are arranged in a mirror image of the normal positioning). "Variants in other genes such as DNAL1 (OMIM: 610062), DNAI1 (OMIM: 604366) and DNAH11 (OMIM: 603339), which are coding for dynein compartments, are known to cause situs inversus-like phenotypes." (PMID 30679815, 2019).
DNAL1 also shares sentences with these, for which no sentence is quoted: tumor (9 papers); carcinoma (7); autoimmune hepatitis (4); lung carcinoma (4); gastric cancer (3); chronic hepatitis C (2); infection (2); Liver Disease (2); myositis (2); neuroblastoma (2); rheumatoid arthritis (2); systemic sclerosis (2); vasculitis (2); viral hepatitis (2); autoimmune disease (1); Autoimmunity (1); bladder (1); breast carcinoma (1); celiac disease (1); chronic hepatitis B (1); E. coli infections (1); giant axonal neuropathy (1); hepatitis C (1); Hypercalciuria (1); liver cancer (1); lung adenocarcinoma (1); lupus (1); melanoma (1); Onset (1); overlap syndromes (1).
A further 11 diseases each share a sentence with DNAL1 in 1 paper.